TMEFF1 (transmembrane protein with EGF like and two follistatin like domains 1)
Diseases named in the same sentence as TMEFF1 in open-access papers (continued):
Sharing a sentence is not in itself a finding about the gene and the disease.
herpes simplex encephalitis (1 paper, 2024). Herpes simplex virus encephalitis (HSE) is caused by the infection of the central nervous system by Herpes simplex virus (HSV) that could have a devastating clinical course and a potentially fatal outcome particularly with delay or lack of treatment. "A study of two childhood cases of herpes simplex encephalitis shows that TMEFF1 interacts with the HSV-1 cell-surface receptor NECTIN-1, preventing HSV-1 from fusing with the cell membrane and entering cortical neurons." (PMID 39048830, 2024).
ovarian serous adenocarcinoma (1 paper, 2024). An adenocarcinoma that arises from the ovary and is characterized by the presence of malignant epithelial cells that, in well differentiated tumors, resemble the epithelium of the fallopian tube or, in poorly differentiated tumors, show anaplastic features and marked nuclear atypia. "By comparing the gene expression profiles of 14 paired ovarian serous adenocarcinoma samples with primary and metastatic (omental) samples, TMEFF1 was determined to be upregulated as an EMT indicator in the metastatic group." (PMID 38468232, 2024).
viral diseases (1 paper, 2024). "Future studies should search for TMEFF1 variants in other patients suffering from HSE and other viral infections of the CNS." (PMID 39048830, 2024). "Inherited TMEFF1 deficiency is also unlikely to underlie viral diseases outside the CNS, given the preferential expression of TMEFF1 in the brain." (PMID 39048830, 2024). "Nevertheless, TMEFF1 deficiency could potentially underlie other viral infections of the CNS, because its cellular effect may not necessarily be specific for HSV-1." (PMID 39048830, 2024).
cancer (6 papers, 2012 to 2025). A tumor composed of atypical neoplastic, often pleomorphic cells that invade other tissues. "One of the targets, Tmeff1, is a type I transmembrane receptor with signal transduction activity and is known to play a role in cancer progression signaling through induction of erbB4 tyrosine kinase receptor phosphorylation and suppression of Nodal signaling." (PMID 22748014, 2012). "However, it is worth noting that the early research into TMEFF1 in cancer indicated that it acts as a cancer suppressor, highly expressed in normal human brain tissues and lowly expressed in brain malignant cancers." (PMID 34475991, 2021). "The positive rate and high expression rate of TMEFF1 in early-stage cancer (I-II) were 76.78% (43 of 56) and 50.00% (28 of 56), respectively, which was significantly lower than those in the late stage (III-IV) (100.00% [19 of 19] and 78.95% [15 of 19]; P=0.021 and 0.027, respectively)." (PMID 34475991, 2021). "TMEFF1 plays a distinctly different role in cancerogenesis in different cancer tissues." (PMID 34475991, 2021). "TMEFF1 (transmembrane protein with EGF-like and two follistatin-like domains) is a member of the Cancer testis antigens (CTAs) family, also known as tomoregulin-1 or TR-1, encoded by the TMEFF1 gene located on chromosome 9q31." (PMID 38468232, 2024). "The EGF-like domain of TMEFF1 can phosphorylate tyrosine of the erbB4 receptor 23, 24, 52, which in turn may activate the MAPK and PI3K/AKT pathways to promote the malignant behavior of cancers." (PMID 34475991, 2021).
tumor (5 papers, 2012 to 2024). "And the expression of MIR503HG was significantly upregulated and TMEFF1 protein level was observably declined in tumor tissues after MIR503HG overexpression." (PMID 35771155, 2022). "In TβRII KO tumor epithelium compared with TβRIIfl/fl epithelium, Igfbp4 and Tspan13 expression was upregulated while Col1α2, Bmp7, Gng11, Vcan, Tmeff1, and Dsc2 expression was downregulated." (PMID 22748014, 2012). "This indicates that TMEFF1 can participate in tumor progression through its interacting proteins." (PMID 34475991, 2021). "Tmeff1 may also be regulated by a fibroblast-secreted factor in the tumor microenvironment." (PMID 22748014, 2012).
infection (1 paper, 2024). The state of being infected such as from the introduction of a foreign agent such as serum, vaccine, antigenic substance or organism. "Enhanced HSV-1 entry into TMEFF1-KO neurons was associated with higher rates of translocation of the virus to the nucleus 10 h after infection." (PMID 39048830, 2024). "As in TMEFF1-KO cortical neurons, high levels of viral replication were detected in the TMEFF1-mutated neurons of the two patients at various time points after infection with HSV-1 at an MOI of 0.001." (PMID 39048830, 2024). "This, in turn, indicates that the extracellular domain of TMEFF1, if produced in a soluble form, would be of potential therapeutic value for combating infections with viruses such as HSV-1, and perhaps also HSV-2, in the CNS or other organs." (PMID 39048830, 2024). "By contrast, TMEFF1-KO neurons displayed similar levels (for EMCV and the measles virus) or slightly higher (HSV-2) levels of infection with the other viruses tested than did WT parental cells." (PMID 39048830, 2024). "By 1 h after infection, higher levels of HSV-1 entry were observed in two clones of TMEFF1-KO neurons than in WT parental neurons or WT neurons differentiated from another healthy control hPSC line." (PMID 39048830, 2024). "Furthermore, bulk RNA-seq on cortical neurons derived from hPSCs from the two patients, TMEFF1-KO and parental WT hPSCs showed that TMEFF1 deficiency did not alter transcriptomic responses to IFNβ after 8 h of stimulation, or those to HSV-1 after 24 h of infection." (PMID 39048830, 2024).
TMEFF1 also shares sentences with these, for which no sentence is quoted: cardiac hypertrophy (2 papers); gastric cancer (2); GM2 gangliosidosis (2); acute myeloid leukemia (1); amyotrophic lateral sclerosis (1); Atrophy (1); atypical endometrial hyperplasia (1); benign tumors (1); cervical cancer (1); colorectal cancer (1); esophageal cancer (1); glioblastoma multiforme (1); glioma (1); head and neck cancer (1); heart failure (1); kidney cancer (1); lung carcinoma (1); melanoma (1); myeloma (1); neurological diseases (1); pancreatic cancer (1); Parkinson disease (1); prostate carcinoma (1); Sandhoff disease (1); sarcoma (1); thyroid carcinoma (1); uterine carcinosarcoma (1); uterine corpus endometrial carcinoma (1).